PTAR1 (protein prenyltransferase alpha subunit repeat containing 1)
Description:
Substrate-recognition subunit of the geranylgeranyl transferase type 3 (GGTase-3) complex. The GGTase-3 complex geranylgeranylates and targets FBXL2 to the cellular membranes, where FBXL2 forms part of the E3 ubiquitin-protein ligase complex SCF(FBXL2) that mediates the degradation of membrane-anchored proteins. The GGTase-3 complex geranylgeranylates Golgi v-SNARE protein YKT6 at 'Cys-194' and this prenylation is required for Golgi SNARE complex assembly.
Tractability: Small molecule: a structure with a bound ligand is known. PROTAC: ubiquitination databases record sites on it; its protein half-life has been measured.
Gene: Protein-coding gene on chromosome 9 (69,709,522 to 69,760,011, reverse strand). Ensembl gene ENSG00000188647.
Subcellular location (Human Protein Atlas): Cytosol; Plasma membrane
Gene Ontology:
Molecular function: protein binding; Rab geranylgeranyltransferase activity; protein prenyltransferase activity
Cellular component: mitochondrion
Genetic constraint (gnomAD): Loss-of-function variants: 8 observed, 28.15 expected, observed/expected ratio (o/e) 0.28, 90% interval 0.17 to 0.51. The upper end of that interval is the gene's LOEUF score, 0.51, which puts it in group 2 of 6, group 1 being the genes least tolerant of losing a copy. Missense variants: 281 observed, 352.44 expected, observed/expected ratio (o/e) 0.8, 90% interval 0.72 to 0.88. Synonymous variants: 124 observed, 128.94 expected, observed/expected ratio (o/e) 0.96, 90% interval 0.83 to 1.12.
Homologues: Orthologues: chimpanzee PTAR1 (99% identical), macaque PTAR1 (99% identical), dog PTAR1 (94% identical), pig PTAR1 (94% identical), rabbit PTAR1 (92% identical), mouse Ptar1 (89% identical), guinea pig PTAR1 (85% identical), rat Ptar1 (81% identical), tropical clawed frog ptar1 (68% identical), zebrafish ptar1 (63% identical), Drosophila melanogaster temp (25% identical). Paralogues in human: RABGGTA (19% identical), FNTA (18% identical).
Diseases named in the same sentence as PTAR1 in open-access papers:
PTAR1 is named in the same sentence as 3 diseases in open-access papers, as found by Europe PMC text mining. Sharing a sentence is not in itself a finding about the gene and the disease. The quoted sentences say what the papers report.
cancer (1 paper, 2020). A tumor composed of atypical neoplastic, often pleomorphic cells that invade other tissues. "Moreover, by comparing the 13 survival-related gene lists, seven genes (SLK, API5, BTBD2, PTAR1, VPS37A, EIF2B1, and ZRANB1) were found to be associated with prognosis in a variety of cancers." (PMID 32300588, 2020).
PTAR1 also shares sentences with these, for which no sentence is quoted: adult T-cell leukemia/lymphoma (1 paper); congenital stationary night blindness (1).